KL (klotho)
Diseases named in the same sentence as KL in open-access papers (continued):
Sharing a sentence is not in itself a finding about the gene and the disease.
chronic kidney disease (continued). "This study explored the relationship between serum Klotho levels and the odds of chronic kidney disease (CKD) in middle-aged and older populations with MetS." (PMID 39777219, 2024). "Shortly after the discovery of Klotho, interest grew in its potential role in chronic kidney disease (CKD)." (PMID 38339121, 2024). "The anti-aging protein Klotho plays a protective role in kidney disease, but its potential as a biomarker for chronic kidney disease (CKD) is controversial." (PMID 38584258, 2024). "Modulating Klotho activity has emerged as a promising therapeutic approach for aging-related conditions, including chronic kidney disease (CKD)." (PMID 39610715, 2024). "This study aims to explore the relationships between serum indoxyl sulfate (IS) and Klotho protein levels with vascular calcification in patients with chronic kidney disease (CKD) stages 3–5." (PMID 38385060, 2024). "Klotho deficiency has been observed in acute kidney injury (AKI) rodent models and patients with chronic kidney disease (CKD)." (PMID 39330350, 2024). "Interestingly, FGF23, which binds to the FGF receptor-Klotho complex, exerts a significant inhibitory effect on Klotho transcription, explaining the observed reduction in Klotho levels in conditions such as chronic kidney disease that elevate FGF23 production." (PMID 40799848, 2024). "Furthermore, patients with chronic renal failure show significantly reduced levels of klotho proteins in the renal tissue, which could be explained by the fact that decreased expression of exacerbation exacerbates interstitial fibrosis." (PMID 38696398, 2024). "This study aimed to investigate the effect of the soluble Klotho (sKlotho)/Wnt/β-catenin signaling pathway on vascular calcification in rat models of chronic kidney disease (CKD) and the intervention effect of Shenyuan granules." (PMID 39230198, 2024). "Studies in clinical studies also have shown low levels of α-Klotho in chronic kidney disease (CKD) and end stage renal disease (ESRD), and low Klotho is reported to be associated with cardiovascular events in hemodialysis patients recently." (PMID 38187354, 2023). "First characterized in the kidney, Klotho rose to prominence as a regulator of the metabolic pathway of chronic kidney disease—mineral and bone disease (CKD-MBD)." (PMID 38067119, 2023). "Single-nucleotide polymorphisms in the klotho gene may help predict non-cardiovascular mortality in patients with chronic kidney disease." (PMID 37587536, 2023). "As the Klotho protein is closely related to aging-related diseases, including cardiovascular disease and chronic kidney disease, increasing dietary fiber intake may have important implications for promoting healthy aging and reducing the risk of these diseases." (PMID 37513564, 2023). "Under normal physiological conditions, the kidney maintains soluble Klotho homeostasis, whereas chronic kidney disease (CKD) patients had lower klotho mRNA expression in the kidney following the decline of kidney function." (PMID 36831276, 2023). "In the kidney, low circulating plasma soluble klotho levels have been correlated with worsening renal function in chronic kidney disease (CKD) and end-stage renal disease (ESRD) as well as in acute kidney injury (AKI)." (PMID 36674838, 2023). "In the early stages of chronic kidney disease (CKD), there is an increased FGF-23-to-klotho ratio which is associated with vascular calcification." (PMID 37441489, 2023). "For example, KL expression has been shown to exert a protective effect against overall mortality in non-diabetic, pre-dialysis chronic kidney disease, whereas FGFR2 expression was associated with increased risk of poor prognosis in patients with IPF and lung cancer." (PMID 37035748, 2023).
chronic kidney disease (continued). "Furthermore, in vivo gene delivery or upregulation of Klotho expression protect against endothelial dysfunction in experimental models of atherosclerosis and ameliorates vascular calcification in an adenine-induced chronic renal failure model." (PMID 37274332, 2023). "The earliest change found in chronic kidney disease (CKD) patients is a decrease in klotho expression, which subsequently leads to a state of resistance, with a compensatory increase in FGF23 preceding the increase in phosphatemia." (PMID 35612845, 2022). "The levels of Klotho decrease with aging and in the case of kidney diseases, such as chronic kidney disease (CKD) and acute kidney injury (AKI)." (PMID 35056905, 2021). "It has been shown that circulatory Klotho levels are significantly lower in patients with chronic kidney disease (CKD) whereas FGF‐23 is elevated." (PMID 32686906, 2020). "The present review summarizes the complex regulation of FGF23 and the disturbed FGF23/Klotho system in chronic kidney disease (CKD)." (PMID 33233840, 2020). "Interestingly, Klotho is highly expressed in the kidney, and its expression is suppressed under sustained stress conditions in several animal models of kidney injury and in patients with chronic renal failure." (PMID 31772699, 2019). "Bone loss and increased fracture are the devastating outcomes of chronic kidney disease-mineral and bone disorder (CKD-MBD) resulting from Klotho deficit-related mineral disturbance and hyperparathyroidism." (PMID 28387374, 2017). "KL knockout mice (KL-/-) develop a syndrome resembling patients with chronic kidney disease (CKD), such as shortened lifespan, hyperphosphatemia, and multiple accelerated age-related disorders including diffusive artery calcification." (PMID 24224012, 2013). "Recently, we have shown that the total amount of urinary excreted soluble Klotho is correlated with the residual renal function among patients with advanced chronic kidney disease (CKD)." (PMID 23176706, 2012). "Chronic kidney disease (CKD) leads to metabolic and cardiovascular complications, and the dysregulation of key biomolecules, namely fibroblast growth factor 23 (FGF23) and Klotho, plays a central role." (PMID 42072635, 2026). "Patients with chronic kidney disease (CKD) often show reduced Klotho expression." (PMID 40636828, 2025). "In chronic renal failure, excess FGF23 and low Klotho promote inflammation and muscle wasting, and Klotho therapy is protective." (PMID 39272986, 2024). "Klotho and IGF1 increase in response to GH treatment in normal subjects and patients with chronic kidney disease." (PMID 38486352, 2024). "Two studies showed the effect of resistance exercise in patients with stage 5 chronic kidney disease on the Klotho-FGF axis, progression and attenuation of chronic kidney disease, iPTH and bone markers 31,32." (PMID 38169578, 2024). "During the early phases of experimental chronic kidney disease (CKD), Klotho expression is decreased." (PMID 37373661, 2023). "Klotho proteins play a protective role for kidneys, and it has been revealed that the blood level of Klotho gradually decreases according to the progression of chronic kidney disease (CKD) in patients." (PMID 38072946, 2023). "Recently, the scenario of possible biomarkers in chronic renal failure has been enriched by new players such as Fibroblast Growth Factor-23 (FGF-23) and Klotho." (PMID 35205271, 2022). "Enhanced inflammation and reduced Klotho are common features in chronic kidney disease (CKD)." (PMID 35299661, 2022). "Furthermore, stratified analyses indicated that the observed associations between DII and serum Klotho concentration were stronger among those aged ≥ 56 years, those with normal weight, and those without chronic kidney disease (P for interaction = 0.003, 0.015, and 0.041, respectively)." (PMID 35761232, 2022).
chronic kidney disease (continued). "In agreement with this hypothesis, it has been shown that s-Klotho levels decrease proportionately with decreasing estimated glomerular filtration rate (eGFR) in both cross-sectional and longitudinal studies performed in patients with chronic kidney disease (CKD)." (PMID 35286490, 2022). "Klotho and fibroblast growth factor 23 (FGF23) are early laboratory parameters of chronic kidney disease (CKD)-mineral bone disorder (MBD), and the Klotho/FGF23 axis plays an important role in this disorder." (PMID 35872753, 2022). "We aimed to evaluate soluble Klotho and circulating fibroblast growth factor 23 (FGF23) ratio as a risk factor for renal progression, cardiovascular (CV) events, and mortality in chronic kidney disease (CKD)." (PMID 35872753, 2022). "In addition, the recently identified biomarker Klotho, which is attributed to have reno-protective characteristics, e.g., by direct binding to the receptor for transforming growth factor beta (TGFβ-R), has been shown to be hypermethylated at its promoter in acute and chronic kidney disease (CKD)." (PMID 34502062, 2021). "However, klotho was reported to decline and to be associated with renal insufficiency following kidney injuries, such as streptozotocin (STZ)-induced hypertensive diabetic nephropathy (DN), chronic kidney disease (CKD), or ischemia/reperfusion acute kidney injury." (PMID 33891667, 2021). "More prolonged dietary Pi for 12 weeks exacerbated kidney senescence and fibrosis; more so in heterozygous Klotho hypomorphic mice compared to wild-type mice, and in mice with chronic kidney disease (CKD) on high Pi diet compared to CKD mice fed a normal Pi diet." (PMID 32973510, 2020). "In humans, circulating levels of soluble Klotho decrease with age, and emerging evidence suggests that Klotho concentration is closely correlated to the development of cardiovascular disease and chronic kidney disease (CKD)." (PMID 32581850, 2020). "Subsequent research is expected to evaluate the role of Klotho and FGF-23 in left ventricular diastolic dysfunction and progression to heart failure in patients with chronic renal disease." (PMID 30934737, 2019). "In chronic kidney disease (CKD), a state of FG23 excess, FGF23 can also bind to FGFR4, independently of KL." (PMID 29085059, 2017). "Klotho is downregulated in chronic kidney diseases (CKD) where aging features are accelerated." (PMID 26583057, 2015). "Elevated serum FGF-23 levels prior to determination of iPTH levels in chronic kidney disease and higher FGF-23 levels in patients with refractory secondary hyperparathyroidism assert the importance of FGF23-Klotho axis." (PMID 25295189, 2014). "KL expression is decreased in the renal tissues of CKD animal models and patients with end-stage renal disease." (PMID 24224012, 2013). "Klotho (KL) expression is down-regulated in the renal tissues of chronic kidney disease (CKD) animal models and patients with end-stage renal disease." (PMID 24224012, 2013). "Compared with the lowest Klotho quintile, cancer individuals with higher Klotho quintiles were younger, less likely to be smokers or alcoholic drinkers, less likely to have CHD or have chronic kidney disease awareness (P < .05)." (PMID 40696614, 2025). "Furthermore, the mediation analysis revealed that chronic kidney disease (CKD), as a form of metabolic abnormality, may play a significant mediating role between Klotho and CVD, consistent with prior evidence." (PMID 40369033, 2025). "Moreover, a decrease in the levels of Klotho in chronic kidney disease (CKD) patients may contribute to the development of kidney injury and fibrosis due to loss of suppression on the Wnt/β-catenin signalling pathway." (PMID 38213484, 2024). "Finally, Klotho is a transmembrane protein produced mainly in the kidney that has antifibrotic and antiapoptotic properties, playing a crucial role in the aging-inflammation binomial of kidney tissue and progression of chronic kidney disease (CKD)." (PMID 36344929, 2022).
chronic kidney disease (continued). "Our study showed that lack of sufficient amounts of Klotho is crucial for mineral metabolism disruptions seen as a complication of chronic kidney diseases." (PMID 33776565, 2021). "Mineral and bone metabolism disorders in chronic kidney disease (CKD-MBD)constitute a syndrome defined by changes in calcium, phosphorus (P), vitaminD and parathormone, fibroblast growth factor 23 (FGF-23) and its specificcofactor, Klotho." (PMID 30534856, 2019). "Surprisingly, the level of Klotho mRNA in the kidney was significantly lower in long-term hypertension, diabetes mellitus, and chronic renal failure, but not after acute myocardial infarction." (PMID 30671457, 2018). "α-klotho (KL), a transmembrane or soluble protein, functions as a co-receptor for Fibroblast Growth Factor (FGF) 23, a known pro-inflammatory, prognostic marker in chronic kidney disease." (PMID 29085059, 2017). "Recent studies suggested a correlation between klotho and calcium levels among elderly patients but not in neonates, healthy children or patients with chronic kidney disease." (PMID 25198618, 2014). "Recently, a study demonstrated that NaHS treatment greatly improved chronic kidney disease (CKD) characterized by hypoxia conditions, restored ten-eleven translocation (TET) activity, reduced DNA methylation, and increased Klotho expression." (PMID 38790620, 2024). "The fibroblast growth factor-23 (FGF-23)–Klotho axis plays a major role in chronic kidney disease-mineral and bone disorder (CKD-MBD) in patients with CKD." (PMID 39839279, 2024). "Moreover, individuals with chronic kidney disease, even in early stages of renal failure, when phosphate and PTH levels were still within the normal ranges, were shown to have increased concentration of FGF23 with a concomitant decrease of serum Klotho." (PMID 34603200, 2021). "Interestingly, in patients with chronic renal failure, the VDR genetic profile seems to perturb the FGF23 expression and consequently the physiological action of FGF23 mediated by FGF receptor and co-receptor Klotho." (PMID 32899460, 2020). "Therefore, parathyroid FGFR1 and klotho expression is decreased in experimental SHP and in end-stage renal disease patients, and this may lead to resistance of the parathyroids to FGF23 in SHP." (PMID 32570711, 2020). "Considering the protective role of Klotho, which was described by several researchers in AKI as well as in chronic kidney disease, the fast increase after the initial stimulus might be explained as a saving response to prevent further inflammation, apoptosis and attenuation of renal injury." (PMID 33033444, 2020). "Since klotho expression is the most abundant in the kidney, patients with kidney diseases, including acute kidney injury (AKI) and chronic kidney disease (CKD), are found to have a significant reduction in klotho expression and soluble levels." (PMID 32545510, 2020). "In addition, serum α-Klotho decreases with the progression of renal dysfunction, which may be attributed to the fact that the membrane protein klotho is expressed predominantly in kidney and brain and that renal expression of klotho is decreased in patients with chronic kidney disease (CKD)." (PMID 25200959, 2014). "Klotho’s renoprotective effects have been demonstrated in the prevention and treatment of ischemia-reperfusion injury-induced acute kidney injury (AKI) and in a chronic kidney disease (CKD) model induced by nephrectomy plus ischemia-reperfusion injury." (PMID 40799848, 2024). "It was demonstrated that in patients with chronic kidney disease (CKD), FGF-23 levels rise in parallel with declining renal function, even before a significant increase in serum phosphate concentration can be detected and a compensatory decrease in Klotho protein concentration is observed." (PMID 34603200, 2021).
renal fibrosis (138 papers, 2011 to 2025). A final common manifestation of a wide variety of chronic kidney diseases characterized by glomerulosclerosis and tubulointerstitial fibrosis. "PAI-1, a reliable marker of senescence, is associated with renal fibrosis, fibrin deposition, and cellular senescence, particularly in Klotho-deficient mice." (PMID 40823556, 2025). "Klotho deficiency makes the kidneys more susceptible to acute injury, delays renal regeneration, and promotes renal fibrosis." (PMID 40134808, 2025). "In parallel, the dysregulation of TGF signaling ultimately contributes to Klotho deficiency and renal fibrosis by inducing the expression of various miRNAs." (PMID 40777989, 2025). "Lastly, klotho deficiency has been associated with cellular senescence and renal fibrosis that is mostly attributed to epithelial-to-mesenchymal transition." (PMID 39281418, 2024). "Clinical investigations have highlighted a significant reduction in Klotho expression in renal fibrosis, indicating an association between Klotho deficiency and the pathogenesis of renal fibrosis." (PMID 39325739, 2024). "Recent studies suggest an association of incipient renal fibrosis with reduced Klotho expression via the WNT/β-catenin signaling pathway." (PMID 38474331, 2024). "Abnormal expression of DNA methyltransferases (DNMT), hypermethylation of Klotho promoter and Klotho inhibition are associated with UUO induced renal fibrosis." (PMID 36235108, 2022). "HDAC4-induced renal fibrosis was associated with renal tubular cell injury and apoptosis, promotion of pEMT, and preserving the Klotho expression at transcriptional levels." (PMID 35847036, 2022). "Klotho deficiency triggers a higher susceptibility toAKI, delays renal regeneration, and enhances renal fibrosis." (PMID 36362179, 2022). "Genistein significantly restored Klotho loss and weakened the renal fibrosis-associated protein expression induced by a unilateral ureteral obstruction in the fibrous kidneys of mice." (PMID 34209224, 2021). "CKD-mineral Bone disorder (CKD-MBD) and renal fibrosis have both been associated with diminished Klotho expression." (PMID 32982966, 2020). "A reduction in Klotho can both be a result and cause of renal fibrosis and can promote a vicious circle of RF generation and mitigation." (PMID 32982966, 2020). "BIX01294-mediated inhibition of renal fibrosis is associated with increased expression of klotho, a renoprotective inhibitor, but BIX01294 treatment did not alter expression of klotho in renal epithelial cells." (PMID 31866860, 2019). "KLOTHO deficiency caused renal fibrosis, whereas the overexpression or injection of KLOTHO ameliorated it." (PMID 31199854, 2019). "Our group and others have confirmed that loss of Klotho protein aggravated kidney fibrosis, while Klotho overexpression improved kidney function and ameliorated renal fibrosis." (PMID 31024315, 2019). "Our current findings represent a novel mechanism underlying the protective effect of Klotho against renal fibrosis in vivo." (PMID 31024315, 2019). "Urinary aminopeptidases and Klotho are early diagnostic biomarkers of renal injury, and urinary levels of these biomarkers are also related with the extent of renal fibrosis in Zucker obese rats." (PMID 30483154, 2018). "Accordingly, demethylation of Klotho gene promoter remarkably reversed renal Klotho deficiency and reduced renal fibrosis." (PMID 30208590, 2018). "Reversal of hypermethylated Klotho promoter associated Klotho suppression by a lipophilic anthraquinone compound, Rhein, has been demonstrated to ameliorate renal fibrosis in unilateral ureter obstruction (UUO)-induced fibrotic kidney mouse model." (PMID 30158531, 2018). "Recent reports have implicated Klotho as an inhibitor of transforming growth factor β1 induced cell migration in renal fibrosis." (PMID 29928482, 2018). "In conclusion, GluAp, AlaAp, and Klotho are early diagnostic markers that are also related with the extent of renal fibrosis in Zucker obese rats." (PMID 30483154, 2018).